MIR320E (microRNA 320e)
Synonyms: hsa-mir-320e
Gene: MicroRNA gene on chromosome 19 (46,709,293 to 46,709,345, reverse strand). Ensembl gene ENSG00000211513.
Gene Ontology:
Biological process: cellular response to glucose stimulus; long-term synaptic potentiation; miRNA-mediated post-transcriptional gene silencing; negative regulation of gene expression; positive regulation of stem cell proliferation
Cellular component: RISC complex
Homologues: Orthologues: chimpanzee MIR320E (100% identical), tropical clawed frog xtr-mir-320 (43% identical). Paralogues in human: MIR320A (91% identical), MIR320C2 (83% identical), MIR320D2 (83% identical), MIR320B1 (81% identical), MIR320B2 (81% identical).